DERL3 (derlin 3)
Diseases named in the same sentence as DERL3 in open-access papers:
DERL3 is named in the same sentence as 33 diseases in open-access papers, as found by Europe PMC text mining. Sharing a sentence is not in itself a finding about the gene and the disease. The quoted sentences say what the papers report.
breast carcinoma (4 papers, 2018 to 2025). "As a key factor in the ER stress response, existing research suggests that the overexpression of DERL3 is associated with aggressive phenotypes in breast cancer cells and is implicated in the occurrence and progression of lung adenocarcinoma." (PMID 40299934, 2025). "The derlin-3 (DERL3) gene’s expression is associated with the progression of breast cancer, and the HSPA5 heat shock protein or BIP has also been implicated in cancer." (PMID 36232621, 2022). "Most recently, increased transcripts of the critical ERAD-associated ubiquitin ligase derlin 3 (DERL3) have been reported in metastatic patient-derived breast cancer samples, correlating with poor disease prognosis." (PMID 30111611, 2018). "Inhibition of DERL3 expression substantially abrogated proliferation and invasiveness in breast cancer cell lines, while pharmacological impairment of two other steps in ERAD by the anti-cancer agents Eeyarestatin I or Bortezomib-promoted cell death in the JeKo-1 mantle cell lymphoma cell line." (PMID 30111611, 2018). "Interestingly, DERL3 expression was found to be positively correlated with MZB1 expression in the clinical specimens from breast cancer patients, suggesting DERL3 may also participate tumor progression." (PMID 34212001, 2021).
lung adenocarcinoma (4 papers, 2020 to 2025). A carcinoma that arises from the lung and is characterized by the presence of malignant glandular epithelial cells. "However, the correlation of DERL3 expression with the malignant phenotype of lung adenocarcinoma (LUAD) cells is unclear and remains to be elucidated." (PMID 36275646, 2022). "The aim of this study is to investigate the ectopic expression of DERL3 in lung adenocarcinoma tissues and its effect on the invasion and metastasis of lung adenocarcinoma A549 cell line to reveal the possible mechanism of invasion and metastasis of lung adenocarcinoma." (PMID 32838486, 2020). "Western blot was used to detect the expression of DERL3 in lung adenocarcinoma cells." (PMID 32838486, 2020). "The expression of DERL3 increased in lung adenocarcinoma (P < 0.05)." (PMID 32838486, 2020).
lung carcinoma (4 papers, 2014 to 2025). "Hypermethylation of DERL3 was potentially associated with early stage of lung cancer and expressed an inclination to indicate better survival outcomes." (PMID 36275646, 2022). "Current research indicates that Derlin-3 plays a role in the development of various cancers, including breast and lung cancer." (PMID 40299934, 2025). "We further explored the correlations between DERL3 and immune cells markers in lung cancer via the TIMER and GEPIA databases." (PMID 36275646, 2022). "Our results identified that DERL3 was upregulated in lung cancer and high expression levels of DERL3 predicted an adverse prognosis of LUAD patients." (PMID 36275646, 2022). "Several studies reported the role of DERL3 as a tumor suppressor in colorectal, gastric, and lung cancers." (PMID 36110953, 2022). "We noticed that DERL3 was significantly upregulated in lung cancer cell lines, especially in the A549 and H1975 cell lines." (PMID 36275646, 2022). "Our results identified that DERL3 might be involved in the pathogenesis of lung cancer and could play an essential role in ERAD process to mediate ER stress." (PMID 36275646, 2022).
colorectal cancer (3 papers, 2014 to 2025). A primary or metastatic malignant neoplasm that affects the colon or rectum. "Overall, these data indicate that the DNA methylation-associated silencing of DERL3 in HCT-116 colorectal cancer cells causes a pro-tumorigenic upregulation of the SLC2A1 protein that can be reversed by restoring DERL3 activity." (PMID 24699711, 2014). "Having observed the CpG island hypermethylation-associated silencing of DERL3 in colorectal cancer cells, we then assayed the ability of DERL3 to function as a suppressor of tumour growth, using in vitro and in vivo approaches." (PMID 24699711, 2014). "In these non-colorectal cancer cell line groups, we also confirmed that the presence of DERL3 CpG island hypermethylation was associated with transcriptional silencing, while unmethylated cell lines expressed the DERL3 transcript." (PMID 24699711, 2014). "Other studies indicate that DERL3 may exert an inhibitory effect in colorectal cancer, while the epigenetic loss of DERL3 induces the overexpression of SLC2A1, thereby influencing tumor progression through the Warburg effect." (PMID 40299934, 2025). "However, one remarkable exception was the AKT inhibitor VIII, for which the presence of DERL3 promoter CpG island hypermethylation was significantly associated with enhanced sensitivity in the panel of 22 colorectal cancer cell lines (multivariate analysis of variance test, FDR<0.01, P=0.003)." (PMID 24699711, 2014). "DERL1 and DERL2 5′-end CpG island were unmethylated in all cases, but DERL3 CpG island promoter hypermethylation was found in four colorectal cancer cell lines: HCT-116, HCT-15, COLO-205 and SW48." (PMID 24699711, 2014). "Derlin 3 (DERL3) is downregulated in colorectal cancer (CRC) samples." (PMID 32838486, 2020). "We confirmed these data in a validation cohort of 73 colorectal cancer cases where the presence of DERL3 hypermethylation assessed by methylation specific was also associated with shorter relapse-free survival (Kaplan–Meier analysis, log rank, P=0.022; hazard ratio 2.60; 95% CI: 1.11–6.10)." (PMID 24699711, 2014). "By contrast, four colorectal cancer cell lines unmethylated at the DERL3 promoter (SW480, SW1116, KM12C and H508) expressed DERL3 RNA." (PMID 24699711, 2014). "The presence of DERL3 cancer-specific promoter CpG island hypermethylation is not an in vitro phenomenon restricted to colorectal cancer cell lines." (PMID 24699711, 2014). "DERL3 epigenetic silencing was not a unique feature of colorectal cancer." (PMID 24699711, 2014).
colon cancer (2 papers, 2014 to 2021). "We confirmed these data in HCT-15 cells, another DERL3-hypermethylated colon cancer cell line, where DERL3 transfection also induced significantly smaller and lighter tumours." (PMID 24699711, 2014). "In a first set of colon tumours (n=91), we found DERL3 hypermethylation determined by methylation-specific PCR in 24% (22 of 91) of patients." (PMID 24699711, 2014).
lung squamous cell carcinoma (2 papers, 2022 to 2025). "DERL3 expression was elevated in the majority of malignant tissues including LUAD and lung squamous cell carcinoma (LUSC)." (PMID 36275646, 2022).
periodontitis (2 papers, 2022 to 2025). An acute or chronic inflammatory process that affects the tissues that surround and support the teeth. "Recent studies have confirmed that DERL3 participates in the pathogenesis of periodontitis by modulating the TLR4/MyD88 pathway through KAT3B-regulated succinylation modification." (PMID 41459503, 2025). "In our study, the significant upregulation of DERL3 in periodontitis patients suggests its potential role as a molecular link connecting endoplasmic reticulum stress to periodontal inflammatory responses." (PMID 41459503, 2025). "We not only identified a novel set of ISR-related biomarkers—BTG2, DERL3, FOS, HSPA13, and YOD1—but also revealed their potential associations with periodontitis-specific pathological features, such as osteoclast differentiation and the RANKL/OPG signaling pathway." (PMID 41459503, 2025). "In this study, BTG2, DERL3, FOS, and HSPA13 were significantly upregulated, and YOD1 was significantly downregulated in the gingival tissues of periodontitis patients, confirming their detectable presence locally." (PMID 41459503, 2025). "In our study, SERPINA1 was the core gene in PPI and correlated with seven ERS-related genes including ERLEC1, VWF, EDEM2, DERL3, APOE, IL6, and CXCL8, suggesting that SERPINA1 may play an essential role in the pathological process of periodontitis." (PMID 36072904, 2022).
anaemia (1 paper, 2014). "Nevertheless, a number of marginal protective genotype associations were also observed between specific gene mutations and anaemia (CFTR, GNAS), hyperparasitaemia (DERL3, GBP7), hyperpyrexia (GBP7, ABO) and SMA (HbS, ADCY9)." (PMID 24934404, 2014).
cervical cancer (1 paper, 2022). A primary or metastatic malignant neoplasm involving the cervix. "Four genes were linked to the prognosis of ferroptosis in cervical cancer, namely, RNF130, CA9, DERL3, and VEGFA, which were obtained by univariate Cox regression analysis in the training set." (PMID 35935576, 2022). "The findings obtained from qRT-PCR illustrated that the expression levels of VEGFA, CA9, and DERL3 in cervical cancer specimens were dramatically elevated in contrast with those in normal specimens, whereas the expression levels of RNF130 were lower contrasted to those in normal specimens." (PMID 35935576, 2022). "However, CA9, DERL3, and VEGFA genes were all upregulated while the opposite was reported for RNF130 in cervical cancer and was linked to unsatisfactory prognosis in the present research." (PMID 35935576, 2022). "In the current study, the novel designed model with four genes (RNF130, CA9, DERL3, and VEGFA) yielded high specificity and sensitivity in identifying prognosis in the cervical cancer." (PMID 35935576, 2022).
colorectal adenocarcinoma (1 paper, 2014). The most common type of colorectal carcinoma. "The analyses of a large collection of primary human colorectal adenocarcinomas showed that DERL3 promoter hypermethylation was common." (PMID 24699711, 2014).
colorectal adenoma (1 paper, 2014). An adenoma that arises from the colon or rectum. "When we examined the DERL3 CpG island methylation status in colorectal adenomas (n=12), a lesion that is a precursor of invasive colorectal tumours, we observed that DERL3 hypermethylation was already present in 33% (4 of 12) of these samples." (PMID 24699711, 2014).
ischemia (1 paper, 2025). A hypoperfusion of the BLOOD through an organ or tissue caused by a PATHOLOGIC CONSTRICTION or obstruction of its BLOOD VESSELS, or an absence of BLOOD CIRCULATION. "Peter J. Belmont’s research highlights that the overexpression of DERL3 can protect myocardial cells from ischemic injury, whereas decreased expression of DERL3 enhances ischemia-induced cardiac cell death." (PMID 40299934, 2025).
leukoplakia (1 paper, 2026). A white patch or plaque on a mucous membrane that cannot be characterized clinically or pathologically as any other disease. "Our previous comprehensive genomic and transcriptomic profiling of leukoplakia and oral squamous cell carcinoma (OSCC) revealed amplification at the 22q11.23 locus, which harbours the DERL3 gene." (PMID 41826880, 2026).
melanoma (1 paper, 2025). A malignant, usually aggressive tumor composed of atypical, neoplastic melanocytes. "Through a combination of bio-informatics analysis and experimental validation, we untangled the functional relevance of key genes (e.g., DTL and DERL3) in melanoma progression and stress adaptation." (PMID 41409301, 2025). "Compared to fibroblasts, prognostic genes were significantly up-regulated in 3 human melanoma cell lines, especially GPX2, DERL3, NDRG1, and DTL (p < 0.05)." (PMID 41409301, 2025).
myocardial infarction (1 paper, 2017). Gross necrosis of the myocardium, as a result of interruption of the blood supply to the area, as in coronary thrombosis. "In addition, DERL3 was implicated in the attenuation of stress response signaling and cell death in myocardial infarction." (PMID 28977827, 2017).
renal carcinoma (1 paper, 2025). A carcinoma arising from the epithelium of the renal parenchyma or the renal pelvis. "In the experimental validation of DERL3’s role in promoting the EMT in renal cancer, we initially utilized only one epithelial cell marker protein." (PMID 40299934, 2025). "However, there are currently no reports addressing the role of DERL3 in renal cancer." (PMID 40299934, 2025).
renal clear cell carcinoma (1 paper, 2025). "In this study, we utilized bioinformatics analysis and in vitro experimental approaches to investigate the role of DERL3 expression in the metastasis of renal clear cell carcinoma cells." (PMID 40299934, 2025). "Additionally, we analyzed the correlation between DERL3 expression and the prognosis of renal clear cell carcinoma patients, while exploring its potential mechanisms of action." (PMID 40299934, 2025).
tumor (12 papers, 2013 to 2025). "DERL3 is involved in the endoplasmic reticulum-associated degradation machinery and functions as a tumor suppressor." (PMID 33255418, 2020). "Most importantly, SLC2A1 overexpression mediated by DERL3 epigenetic loss contributes to the Warburg effect in the studied cells and pinpoints a subset of human tumours with greater vulnerability to drugs targeting glycolysis." (PMID 24699711, 2014). "The observed SLC2A1 overexpression induced by DERL3 epigenetic loss generates a Warburg effect in the studied cells and it highlights a group of human tumours that are more sensitive to drugs targeting glycolysis." (PMID 24699711, 2014). "Here we demonstrate the presence of promoter CpG island hypermethylation-linked inactivation of DERL3 (Derlin-3), a key gene in the endoplasmic reticulum-associated protein degradation pathway, in human tumours." (PMID 24699711, 2014). "We demonstrate for the first time that DERL3 promotes tumor progression in ccRCC, showing significantly elevated expression, especially in metastatic ccRCC cell lines." (PMID 40299934, 2025). "DERL3 expression profiles were identified in tumor and normal tissues according to TCGA transcriptomic data." (PMID 36275646, 2022). "According to the relevant DERL3 expression in tumor tissues, 294 LUAD patients were classified into the DERL3 low expression group (n = 144) and high expression group (n = 150)." (PMID 36275646, 2022). "In the present study, bioinformatics techniques were applied to comprehensively elaborate the pathway enrichment and immune infiltration of DERL3 in a tumor microenvironment (TME)." (PMID 36275646, 2022). "DERL3 loss leads to SLC2A1 (glucose transporter 1, GLUT1) overexpression, which contributes to the Warburg phenomenon of tumor cells." (PMID 27359056, 2016). "Overall, the findings presented here suggest tumour suppressor and dissemination inhibitor roles for DERL3." (PMID 24699711, 2014). "The restoration of in vitro and in vivo DERL3 activity highlights the tumour suppressor features of the gene." (PMID 24699711, 2014). "Some of these, such as the DERL3 gene, also promote tumor progression." (PMID 36232621, 2022). "It indicated that DERL3 might help the tumor evade from immune surveillance by upregulating immune checkpoint molecules of TME in LUAD." (PMID 36275646, 2022). "Interestingly, although all (12 out of 12, 100%) empty vector orthotopics were able to locally colonize to the peritoneal cavity of the mice, only one (8%) of the DERL3-transfected tumours had this ability." (PMID 24699711, 2014). "Finally, we found that SLC2A1 exerted an important role in the tumour suppressor effects mediated by DERL3." (PMID 24699711, 2014). "Particularly, the methylation of Derl3 and Herp was reduced in the tumor portion of older KOs, methylation of Creld2, Wfs, and Yod1 was not changed in the normal liver portion, and mRNA expression of Hrd1 and Yod1 was remarkably increased in both liver and tumor portions of KO with liver tumors." (PMID 24198826, 2013). "The expression of DERL3 was identified to be correlated with tumor stage (p = 0.032) and T stage (p = 0.024) but not with other clinical characterizations." (PMID 36275646, 2022). "However, it has not been reported whether the other four genes, NCAPG, S100A2, DERL3, and COL22A1, exert any biological role in the interaction between tumor and immune cells." (PMID 34136486, 2021). "In addition, the methylation of Derl3, Herp and Yod1 was increased in the normal liver portion of tumor bearing livers of older KO compared to older KO without liver tumors." (PMID 24198826, 2013). "In the tumor bearing livers, the methylation of Derl3, Herp, and Yod1 was reduced in the tumor portion compared to the normal liver portion whereas the methylation of Creld2 or Wfs was not significantly changed in the tumor portion compared to the liver portion." (PMID 24198826, 2013).
tumor (continued). "The IHC data revealed that the expression of VEGFA, CA9, and DERL3 in CC specimens was more obvious as opposed to that in normal samples, while the expression of RNF130 was decreased in tumor tissues." (PMID 35935576, 2022).
cancer (8 papers, 2014 to 2025). A tumor composed of atypical neoplastic, often pleomorphic cells that invade other tissues. "DERL1, DERL2 and DERL3 are gene candidates for hypermethylation-associated inactivation in human cancer because a 5′-CpG island is located around their transcription start sites." (PMID 24699711, 2014). "Having noted the DERL3 promoter hypermethylation in cancer cell lines, we assessed its association with the putative transcriptional inactivation of the DERL3 gene at the RNA and protein levels." (PMID 24699711, 2014). "It was indicated that DERL3 was predominantly elevated in carcinoma compared with adjacent tissues in multiple kinds of tumors from the TCGA database, especially in LUAD." (PMID 36275646, 2022). "Clinical LUAD samples including carcinoma and adjacent tissues were obtained and were further extracted to detect DERL3 mRNA expression via RT-qPCR." (PMID 36275646, 2022). "Overall, the findings suggest that DERL3-hypermethylated cancer cells undergo glucose-dependent growth mediated by SLC2A1 that renders them highly sensitive to particular glycolysis inhibitors." (PMID 24699711, 2014). "The finding that DERL3-hypermethylated cancer cells were highly sensitive to shikonin, and that restoration of DERL3 expression induced resistance to this drug was further confirmed by an MTT growth inhibition curve, the SRB (Sulforhodamine B) assay and colony formation experiments." (PMID 24699711, 2014). "The dependence of DERL3 epigenetically silenced cells on glucose prompted us to examine whether these cells were more sensitive to small drugs that target cancer metabolism, particularly glycolysis." (PMID 24699711, 2014). "Therefore, investigating the significance of DERL3 in the pathogenesis of ccRCC may aid in identifying new therapeutic targets for this cancer." (PMID 40299934, 2025). "Thus, we wondered whether SLC2A1 expression levels mediated by DERL3 degradation affected cancer cell glucose-dependent growth and lactate production." (PMID 24699711, 2014). "It was noted that three of the four genes, i.e., MZB1, DERL3, and PSMD3, were more highly expressed in cancer tissues than in adjacent normal lung tissues." (PMID 34212001, 2021). "The cancer cell lines HCT-116, HCT-15, COLO-205 and SW48, hypermethylated at the DERL3 CpG island, had minimal expression of the DERL3 RNA transcript, as determined by conventional and quantitative reverse transcription-PCR." (PMID 24699711, 2014).
infectious disease (1 paper, 2011). A disorder directly resulting from the presence and activity of a microbial, viral, or parasitic agent in humans. "There does not appear to be any previous study linking mutations in Derl3 to the control of infectious disease." (PMID 21867552, 2011).
DERL3 also shares sentences with these, for which no sentence is quoted: bladder cancers (1 paper); cholangiocarcinoma (1); colorectal tumours (1); endometrial cancer (1); gastric cancer (1); hepatocellular carcinoma (1); leukaemia (1); malaria (1); multiple myeloma (1); Oral Cancer (1); oral squamous cell carcinoma (1); thyroid cancer (1); Wolfram syndrome (1).